RN7SKP127 (RN7SK pseudogene 127)
Gene: Miscellaneous RNA gene on chromosome 16 (29,731,051 to 29,731,404, reverse strand). Ensembl gene ENSG00000222375.
Homologues: Orthologues: chimpanzee 7SK (99% identical), guinea pig 7SK (50% identical). Paralogues in human: RN7SKP203 (68% identical), 7SK (67% identical), RN7SKP176 (67% identical), RN7SKP77 (67% identical), RN7SKP79 (67% identical), RN7SKP249 (66% identical), RN7SKP124 (65% identical), RN7SKP160 (65% identical), RN7SKP296 (65% identical), RN7SKP189 (65% identical), RN7SKP217 (65% identical), RN7SKP71 (65% identical), and 284 more.